SERPINA3 (serpin family A member 3)
Diseases named in the same sentence as SERPINA3 in open-access papers (continued):
Sharing a sentence is not in itself a finding about the gene and the disease.
schizophrenia (20 papers, 2007 to 2024). A major psychotic disorder characterized by abnormalities in the perception or expression of reality. "For example, in the brain SERPINA3 is mainly expressed by astrocytes, and its deregulation has been linked to the pathogenesis of several diseases, including schizophrenia and Alzheimer’s." (PMID 33375642, 2020). "SERPINA3 mRNA was increased by 414% (F = 21.49, df = 1,52, p < 0.0001) in schizophrenia cases relative to controls and TNFα mRNA was increased by 132% (F = 3.90, df = 1,53, p = 0.050) in cases compared with controls." (PMID 31168068, 2021). "SERPINA3 was also found to be up-regulated in patients’ brains of schizophrenia and all human prion diseases, signifying the involvement of SERPINA3 in the pathogenesis and progression of prion like fatal neurodegenerative disorders." (PMID 33662018, 2021). "We found diagnostic increases in SERPINA3, TNFα, IL1β, IL6, and IL6ST transcripts in schizophrenia compared with controls (p < 0.02–0.001)." (PMID 31168068, 2021). "We found marked diagnostic increases in the transcripts of pro-inflammatory cytokines (IL6 and IL1β) and in an acute-phase protein (SERPINA3) in the schizophrenia midbrain." (PMID 31168068, 2021). "There were also moderately strong, significant correlations of KATI mRNA with IL-6 and SERPINA3 mRNAs in people with schizophrenia in the SMRI cohort." (PMID 30940904, 2020). "In contrast, we detected moderately strong, significant inverse correlations of KMO mRNA levels to IL-1β and SERPINA3 mRNA levels within the PFC of people with schizophrenia." (PMID 30940904, 2020). "In the TRC cohort, there were moderately strong, positive, significant correlations between KAT I/II mRNAs and many cytokines assessed (IL-1β, IL-6, and IL-8) and SERPINA3 in schizophrenia and control groups." (PMID 30940904, 2020). "The mRNA level of SERPINA3 is robustly up-regulated in the prefrontal cortex of schizophrenia patients, suggesting its involvement in the pathogenesis of neuropsychiatric disorders." (PMID 31447881, 2019). "Despite the variability, some studies evaluating neuroinflammation in postmortem brains in schizophrenia suggest an increase in microglial activity and other markers such as SERPINA3 and IFITM." (PMID 27271499, 2016). "The volumes of cortical grey matter and SFG were significantly negatively correlated with IL-6 and SERPINA3 mRNAs for both the whole cohort and the schizophrenia group only (all −0.700<r<−0.341, P<0.01)." (PMID 27959331, 2016). "We tested this hypothesis by measuring transcripts of several pro-inflammatory cytokines and the acute-phase protein, serpin family A member 3 (SERPINA3), in postmortem tissue encompassing the substantia nigra of schizophrenia cases and matched controls." (PMID 31168068, 2021). "A secondary network analysis of significantly altered focus and reference proteins associated the IL-1 receptor with SERPINA3, GABRG2, GAD2, and IRAK1 with schizophrenia and related disorders (early-onset schizophrenia, schizoaffective disorder, and psychosis)." (PMID 33976392, 2021). "Therefore, we investigated inflammation in the SEZ by defining those with low and high levels of inflammation using cluster analysis of IL6, IL6R, IL1R1 and SERPINA3 gene expression in 32 controls, 32 schizophrenia and 29 bipolar disorder cases." (PMID 34911938, 2021). "Furthermore, in the schizophrenia group, SERPINA3 (ρ=0.397, P=0.016) and IL-6 (ρ=0.464, P=0.004) mRNAs were significantly positively correlated with antipsychotic (lifetime) intake." (PMID 27959331, 2016). "As it has been suggested that schizophrenia may be the consequence of a vascular-inflammation, we studied the mRNA levels of SERPINA3, IFITM2, IFITM3, and GBP1 in a human endothelial cell line (TIME), before and after stimulation with TNF-α." (PMID 17822540, 2007).
schizophrenia (continued). "Thus, it appears that the widespread and consistent upregulation of SERPINA3 mRNA and protein in schizophrenia may be an attempt to maintain the homeostasis of the CNS in response to a peripheral stimulus." (PMID 27898074, 2016). "Duration of illness positively correlated with IL6, IL6R and SERPINA3 mRNAs and negatively correlated with P2RY12 mRNA in schizophrenia." (PMID 34911938, 2021). "Age of onset negatively correlated with CD14, IL6R, IL1R1, SERPINA3, pan-GFAP and VIM mRNAs in schizophrenia and CD14, IL1B, SERPINA3, pan-GFAP and VIM mRNAs in bipolar disorder." (PMID 34911938, 2021). "In schizophrenia, IL1B and SERPINA3 mRNAs positively correlated and P2RY12 mRNA negatively correlated with standardised lifetime antipsychotic dose (all p ≤ 0.022)." (PMID 34911938, 2021). "(II) In schizophrenia, transcriptome analysis of brain tissue from autopsy of schizophrenic patients showed an increased expression of IFITM2, IFITM3, SERPINA3, and GBP1 was found." (PMID 29181395, 2017). "For individuals with schizophrenia, each inflammatory mRNA in OFC tissue was significantly correlated with its expression in the DLPFC tissue (SERPINA3 r=0.723, P<0.001; IL-1β r=0.744, P<0.001; IL-6 r=0.686, P<0.001; IL-8 r=0.417, P=0.022)." (PMID 27959331, 2016). "Despite this heterogeneity, microarray analyses have consistently indicated markers such as SERPINA3 and IFITM to be elevated in schizophrenia." (PMID 27271499, 2016). "In particular, IFITM2, IFITM3, SERPINA3, and GBP1 showed increased mRNA levels in schizophrenia (p-values from qPCR ≤ 0.01)." (PMID 17822540, 2007). "We also found that IL-6, SERPINA3 and IL-1β mRNA levels had significantly negative relationships with the volume reduction in schizophrenia, suggesting that increases in at least these three factors are linked to reduced brain volumes." (PMID 27959331, 2016). "Our results give additional support to the inflammatory hypothesis for schizophrenia and provide four biological markers for the disease likely to be directly involved in inflammatory processes, namely GBP1, SERPINA3, IFITM2, and IFITM3." (PMID 17822540, 2007). "Other proinflammatory markers such as substance P, NF-κB, SERPINA3, and interferon-induced transmembrane protein (IFITM) were found elevated in concentration and/or expression in certain brain regions in schizophrenia patients in some, though not all, studies." (PMID 29181395, 2017). "Both these analyses confirmed that mRNA levels of SERPINA3, IFITM2, IFITM3 and GBP1 were increased in schizophrenia and were not simply the consequence of an infection immediately prior to death." (PMID 17822540, 2007).
glioma (18 papers, 2018 to 2026). A benign or malignant brain and spinal cord tumor that arises from glial cells (astrocytes, oligodendrocytes, ependymal cells). "This study showed that SERPINA3 expression is associated with glioma malignancy, including higher grade tumours and shorter patient survival time." (PMID 34449972, 2021). "Previous studies have demonstrated that SERPINA3 expression is significantly enhanced in glioma and associated with poor prognosis for glioma patients, moreover, its expression have the potential to suppress the activation of CD4+ T cells, monocytes and Mast cells." (PMID 41550507, 2026). "In addition, high SerpinA3 expression in glioma tissues was shown to be associated with poor survival." (PMID 38279150, 2024). "However, it has also reported that upregulation of SERPINA3 is significantly associated with glioma progression and poor patient survival." (PMID 36000536, 2022). "However, the relationship between SERPINA3 and glioma malignant progression, as well as its association with GAMs infiltration, remains unclear." (PMID 41550507, 2026). "We reported that SERPINA3 have the potential to enhance GAMs infiltration in glioma specimens, further remodeling glioma immune microenvironment." (PMID 41550507, 2026). "In this study, we firstly evaluated SERPINA3 levels in clinical glioma tissues and evaluated the relationship of SERPINA3 with the glioma grade." (PMID 41550507, 2026). "We found that an upregulated of SERPINA3 protein expression in GBM tissues compared to low-grade gliomas." (PMID 41550507, 2026). "SERPINA3 expression displayed a positive association with CD68 and IBA1 in primary gliomas, as evidenced by the data." (PMID 41550507, 2026). "Our study underscores the association between SERPINA3 expression and glioma grade, as well poor prognosis, it is suggested that SERPINA3 has the potential to promote glioma malignant progression." (PMID 41550507, 2026). "In this study, we explored SERPINA3 levels in different grade glioma tissues and its correlation with GAMs markers." (PMID 41550507, 2026). "Our results demonstrated that SERPINA3 expression level in WHO IV glioma tissues were significantly increased compared with other WHO grade tissues, indicating potential malignant progression." (PMID 41550507, 2026). "Our study revealed that SERPINA3 is upregulated in high-grade glioma tissues and correlates with poor survival outcomes in glioma patients." (PMID 41550507, 2026). "Herein, for the first time, a thorough investigation was conducted into the regulatory role of SERPINA3 in GAMs within glioma tissues." (PMID 41550507, 2026). "In our study, increased SERPINA3 expression correlates with glioma grade and poorer survival outcomes." (PMID 41550507, 2026). "Nonetheless, comprehensive analysis of large-scale datasets and in-depth mechanistic studies are essential to confirm the role of SERPINA3 in glioma." (PMID 41550507, 2026). "This research provides promising insights into SERPINA3 as a novel biomarker and potential therapeutic direction in glioma patients." (PMID 41550507, 2026). "Intriguingly, within GBM tissues, we further confirmed the expression of SERPINA3 in GAMs, and that SERPINA3 expression is positively associated with CD68 and IBA1 in primary gliomas, indicating remodeling of the tumor immune microenvironment." (PMID 41550507, 2026). "Kaplan-Meier survival analysis revealed an inverse correlation between SERPINA3 expression and prognosis in primary glioma patients from the CGGA database." (PMID 41550507, 2026). "In brief, we suggest that SERPINA3 expression contributes to glioma malignant progression and TAMs infiltration." (PMID 41550507, 2026). "Previous research revealed that elevated SERPINA3 expression portends a dismal prognosis for glioma patients." (PMID 41550507, 2026). "In clinical studies, SerpinA3 expression was increased in various tumor tissues, including colon, lung adenocarcinoma, breast and glioma." (PMID 38279150, 2024).
glioma (continued). "For example, SerpinA3 knockdown in vitro showed decreased glioma or colon cancer cell proliferation, invasion, and migration, and its expression showed a positive correlation with poor patient prognosis." (PMID 37422673, 2023). "The overexpression of SERPINA3 is also positively correlated with glioma development, as well as its size, stage (WHO grade), and negative prognosis." (PMID 36672665, 2023). "The increased level of SERPINA3 in breast, colon, and prostate cancers, as well as glioma, proves that theory." (PMID 36672665, 2023). "SERPINA3 is predominantly localized in cytoplasm in glioma, melanoma, lung and colon tumor tissues where its high expressions are associated with poor prognosis." (PMID 37414914, 2023). "Results of RISH showed that SERPINA3 was of high expression in 25.4% (68/267) of the tested gliomas." (PMID 34449972, 2021). "In the present study, the expression of SERPINA3 mRNA was first detected in 321 glioma and 13 normal tissues by RNA in situ hybridization." (PMID 34449972, 2021). "This study is expected to provide valuable information on the role of SERPINA3 as a novel biomarker and potential target in glioma." (PMID 34449972, 2021). "Further, we validated the expression and the survival prediction role of SERPINA3 by using tissue microarrays and RNAscope in situ hybridization in 321 gliomas." (PMID 34449972, 2021). "The relationship between SERPINA3 levels and the survival, clinical parameters, and expression of other biomarkers of glioma patients was analysed." (PMID 34449972, 2021). "We observed that serpin peptidase inhibitor clade A member 3 (SERPINA3) messenger RNA was overexpressed in glioma tissues and involved in proliferation procession of glioma cells." (PMID 34449972, 2021). "These analyses showed that SERPINA3 can play a significant role in predicting the survival of glioma patients." (PMID 34449972, 2021). "The present study demonstrates that SERPINA3 is overexpressed in glioma tissues and is involved in the proliferation of glioma cells." (PMID 34449972, 2021). "Herein, the role of SERPINA3 in the regulation of the tumour microenvironment in glioma tissues was analysed in detail for the first time." (PMID 34449972, 2021). "Result of univariate and multivariate Cox analyse indicated that high expression of SERPINA3 was an indepent shorter survival indicator for glioma patients." (PMID 34449972, 2021). "Herein, the proportion of SERPINA3 overexpression in glioma tissues ranged from 17.6%–52.3% in different datasets." (PMID 34449972, 2021). "Nonetheless, analysis of large‐scale dataset and mechanistic studies are still needed to validate the function of SERPINA3 in glioma." (PMID 34449972, 2021). "We analyzed the biological functions of SERPINA3 through data from the Chinese Glioma Genome Atlas databases." (PMID 34449972, 2021). "Our study was designed to explore the value of SERPINA3 messenger RNA (mRNA) expression in the biological process, prognosis, and immune significance in glioma." (PMID 34449972, 2021). "SERPINA3 is known to be elevated in glioma tissues at both the mRNA and protein levels, compared with noncancerous brain tissues." (PMID 29513714, 2018). "Taken together, these results demonstrate that SERPINA3 may promote the malignant progression of glioma." (PMID 41550507, 2026). "•SERPINA3 promotes infiltration of GAMs in glioma, suggesting remodeling of TIME." (PMID 41550507, 2026). "•This study provides glioma patients with novel strategy targeting SERPINA3." (PMID 41550507, 2026). "This study provides an insight into the therapeutic strategy targeting SERPINA3 in glioma patients." (PMID 41550507, 2026). "•In human glioma tissues, SERPINA3 expression is found in GAMs." (PMID 41550507, 2026). "Therefore, SERPINA3 emerges as a potential therapeutic target and prognostic marker for glioma patients." (PMID 41550507, 2026). "The level of SERPINA3 protein correlates with low infiltration of glioma tissue by CD4+ cells." (PMID 36672665, 2023).
glioma (continued). "Based on these findings, whether SERPINA3 affects CD4+ T cells in glioma by affecting STAT3 should be further investigated." (PMID 34449972, 2021). "Overexpression of SERPINA3 mRNA in high grade gliomas suggests that SERPINA3 may play a key role in the progression of glioma cells." (PMID 34449972, 2021). "High levels of SERPINA3 correlated with poor survival in patients with glioma." (PMID 34449972, 2021). "Taken together, these results indicate that SERPINA3 may promote the proliferation and strengthen the malignant progression of glioma cells." (PMID 34449972, 2021). "SERPINA3 participate in promoting immune suppression in glioma TME." (PMID 34449972, 2021). "Moreover, a survival prediction model based on SERPINA3 mRNA expression and other factors in glioma patients was established for the first time." (PMID 34449972, 2021). "A strong correlation between the expression of SERPINA3 and these molecules in glioma suggests that SERPINA3 may participate in the proliferation of glioma cells." (PMID 34449972, 2021). "In addition, the threshold of high expression was determined based on the prognostic analysis of various datasets, with glioma patients with high SERPINA3 expression tending to have poor survival." (PMID 34449972, 2021). "Given that SERPINA3 levels were herein negatively correlated with the number of M1 macrophages, suggests that SERPINA3 may downregulate the inflammatory reaction of glioma cells." (PMID 34449972, 2021). "And overexpression of SERPINA3 correlated with low CD4+ T cell infiltration in glioma tissues." (PMID 34449972, 2021). "SERPINA3 may play a key role in the biological process of glioma cells especially in immune suppression activities." (PMID 34449972, 2021). "To confirm that c-JunDN could in fact suppress c-Jun function in U251 cells, we examined the expression of two genes that are regulated by AP-1 transcriptional complexes in astrocytes and glioma cells; SERPINA3 (α1-antichymotrypsin) and GFAP." (PMID 30651087, 2019). "Furthermore, the biological function of SERPINA3 in glioma cells was explored." (PMID 34449972, 2021). "Moreover, SERPINA3 promotes immune suppression in the glioma microenvironment." (PMID 34449972, 2021). "SERPINA3 could serve as a novel prognosis biomarker and therapy target in glioma." (PMID 34449972, 2021). "SERPINA3 may serve as an independent survival prediction factor in glioma patients." (PMID 34449972, 2021). "Moreover, expression of SERPINA3 correlated with low CD4+ T cell infiltration in glioma tissues." (PMID 34449972, 2021). "The data demonstrated that co-expression of CD68/SERPINA3 and IBA1/SERPINA3 in glioma specimens, indicating SERPINA3 expression in GAMs." (PMID 41550507, 2026). "Further, we examined the relation of SERPINA3 and these molecules in WHO II, III and IV gliomas form CGGA datasets and the mRNA level of SERPINA3 showed a positive correlation with CD68." (PMID 41550507, 2026). "Analyzing CGGA data, we observed a positive correlation between SERPINA3 mRNA expression and the levels of CD68 and IBA1 mRNA in primary gliomas, suggesting a link between SERPINA3 and GAM markers." (PMID 41550507, 2026). "To explore the molecules that influence prognosis, we further mining the survival data from the public databases about SERPINA3, CD68 and IBA1 for glioma patients." (PMID 41550507, 2026). "A total of 1339 patients with confirmed glioma (CAMS: 321 gliomas; CGGA:1018 gliomas) were collected the SERPINA3 mRNA expression data." (PMID 34449972, 2021). "To further test the correlation between SERPINA3 mRNA expression and the tumor immune infiltrating of CD4+ T cell in tissues, we performed the IHC experiment in 20 gliomas." (PMID 34449972, 2021). "Thus, SERPINA3 may serve as a novel prognostic biomarker and therapeutic target in glioma." (PMID 34449972, 2021). "Further the level of SERPINA3, CD68 and IBA1 with prognosis are detected in glioma patients." (PMID 41550507, 2026).